ADAMTS13 (ADAM metallopeptidase with thrombospondin type 1 motif 13)
Diseases named in the same sentence as ADAMTS13 in open-access papers (continued):
Sharing a sentence is not in itself a finding about the gene and the disease.
Sepsis (continued). "The stored blood samples were estimated for TNF-α, A Disintegrin and Metalloproteinase Motifs 13 (ADAMTS13), and soluble Fas ligand (FasL) at the end of the study to confirm the biomarker-based inflammatory phenotypes of sepsis-induced MOFS." (PMID 41883885, 2026). "Sepsis disrupts the delicate balance between vWF and the enzyme known as a disintegrin and metalloproteinase with thrombospondin type 1 motif 13 (ADAMTS13), leading to lower ADAMTS13 activity in a background of elevated vWF levels." (PMID 40003683, 2025). "Previous studies have shown that elevated interleukin-6 levels, among other proinflammatory cytokines, directly correlate with decreased ADAMTS13 activity in patients with sepsis." (PMID 40725629, 2025). "Several studies indicate that over one-third of patients with sepsis exhibit ADAMTS-13 levels that are two times lower than normal, with approximately 15% of patients showing levels below 10% of normal." (PMID 40244141, 2025). "Systemic inflammatory responses, such as sepsis, pancreatitis, and trauma, decrease ADAMTS13 activity." (PMID 39039520, 2024). "The findings indicate that IntelliSep, combined with plasma vWF/ADAMTS13 ratio, holds promise for enhancing early sepsis detection and treatment in emergency scenarios." (PMID 39200994, 2024). "Sepsis is characterized by decreased ADAMTS-13 activity, which results in increased thrombogenic ultra-large von Willebrand factor (ULvWF) multimers and potentially diffuse microcirculatory platelet thrombosis." (PMID 38178170, 2024). "In critical illnesses such as trauma, sepsis, and burns, plasma vWF significantly increases and is accompanied by a concomitant decrease in ADAMTS13 (a disintegrin and metalloprotease with thrombospondin type-1 repeats 13) activity." (PMID 39200994, 2024). "Endothelial vWF and ADAMTS13 are important regulators of hemostasis, but their dysregulation during sepsis remains poorly studied." (PMID 39200994, 2024). "The presence of a concurrent cancer diagnosis or sepsis was observed in a significant proportion of cases (40%) where a discrepancy in ADAMTS13 results was found." (PMID 39124729, 2024). "Nevertheless, our study is unique in that we compared the ISI with other markers of sepsis, including the MDW, serum lactate level, and vWF/ADAMTS13 ratio, which provides mechanistic insight into the various biomarkers used for assessing sepsis." (PMID 39200994, 2024). "As a result, we also measured the plasma levels of vWF and ADAMTS13 antigen in these patients and correlated these biomarkers with the sepsis score and IntelliSep ISI." (PMID 39200994, 2024). "It is worth noticing that, to the best of our knowledge, this is the first study assessing ADAMTS-13 levels in neonatal sepsis and elucidating the delicate implication of ADAMTS-13 in neonatal-sepsis-induced coagulopathy." (PMID 37886991, 2023). "In acute iTTP patients, the ADAMTS13 conformation is open, whereas the evaluation of healthy individuals, sepsis patients, and hemolytic uremic syndrome (HUS) patients all showed a closed conformation." (PMID 37834813, 2023). "ADAMTS13 becomes inactivated during sepsis, resulting in incomplete VWF cleavage, thereby increasing blood viscosity and stasis." (PMID 37159776, 2023). "In contrast with other types of sepsis, an increase in the vWF/ADAMTS-13 ratio was observed, and a significant inverse correlation between vWF : Ag levels and ADAMTS-13 activity." (PMID 35719336, 2022). "Von Willebrand Factor (VWF) and ADAMTS13 are important regulators of hemostasis and their dysregulation during sepsis progression is not well understood." (PMID 33606732, 2021). "Alternatively, there are slightly or moderately decreased ADAMTS13 activities with secondary thrombotic disorders such as sepsis or other conditions." (PMID 33712048, 2021).
Sepsis (continued). "On the other hand, some acute critical diseases such as sepsis are often complicated by a secondary mild to moderate decrease in ADAMTS13 levels, which is thought to be one of the heterogenic reactions, even without the development of TMA or TTP." (PMID 33712048, 2021). "Patients with sepsis, patients admitted to the Intensive Care Unit, and patients in need of mechanical ventilator support had significantly lower levels of ADAMTS-13." (PMID 31434239, 2019). "Patients with sepsis had significantly lower levels of ADAMTS-13, and its area under the curve (AUC) to predict sepsis in patients with SBI was 0.67 (95% confidence interval (CI) 0.545 to 0.774, p = 0.013)." (PMID 31434239, 2019). "A cut-off ADAMTS-13 level of ≤730.49 had 82% sensitivity and 60% specificity for sepsis in patients with SBI." (PMID 31434239, 2019). "The clinical relevance of ADAMTS-13 during sepsis is still unclear, although ADAMTS-13 and its role in sepsis have been studied in the pediatric population, where it has been associated with disease severity and outcome." (PMID 31434239, 2019). "Other authors have studied ADAMTS-13 activity in patients with severe sepsis and septic shock and compared those with healthy controls." (PMID 31434239, 2019). "ADAMTS13 activity is decreased in many diseases associated with vascular inflammation or occlusion, such as cancer, TTP, sepsis, malaria and HUS5,47,48." (PMID 30026593, 2018). "VWF, ADAMTS13 and platelets have been suggested as possible biomarkers for microangiopathic diseases such as sepsis." (PMID 28296884, 2017). "This is in line with other findings demonstrating an improved survival in patients with severe sepsis with higher levels of ADAMTS-13 activity." (PMID 28775254, 2017). "Some cases of ADAMTS13 deficiency have been reported recently in adult patients with sepsis-induced DIC and this ADAMTS13 deficiency was associated with acute renal failure." (PMID 24238574, 2013). "Therefore, ADAMTS-13 may be used as a diagnostic marker in patients with sepsis." (PMID 23537039, 2013). "This raises the possibility of novel therapeutic strategies for patients with sepsis including plasma infusion; ADAMTS-13 supplementation and synthetic granulocyte elastase inhibitors." (PMID 23537039, 2013). "One of the studies showed that ADAMTS-13 activity was significantly lower in patients with severe sepsis and patients above the median of ADAMTS-13 activity presented a higher survival compared with those below the median activity." (PMID 23537039, 2013). "Second, direct catalytic inhibition of ADAMTS13 by IL-6, a cytokine highly secreted in sepsis, has been reported in vitro using ULVWF strings secreted from human umbilical vein endothelial cells under flowing conditions." (PMID 24238574, 2013). "Median ADAMTS13 antigen levels were comparable between patients and controls, except for higher values in patients with acute liver failure or acute liver injury and lower levels in those with acute-on-chronic liver failure and sepsis." (PMID 41035784, 2025). "In sepsis patients, ADAMTS13 is depleted primarily through cytokine-mediated suppression." (PMID 40725629, 2025). "Several other factors that occur during sepsis and inflammation can inhibit ADAMTS13 activity." (PMID 39857914, 2025). "Up to one-third of patients with sepsis have ADAMTS13 levels that are < 50% of normal." (PMID 39200994, 2024). "Next, they examined the role of the vWF and ADAMTS13 ratios in assessing the likelihood of sepsis." (PMID 39200994, 2024). "Notably, the level of ultra-large vWF multimers in patients with sepsis is inversely correlated with the ADAMTS13 level." (PMID 39274365, 2024). "Usually, UL-VWF is broken by ADAMTs13 into small multimers, however, in patients with sepsis, ADAMTs13 is reduced, being unable to break these long structures which originate in a string surrounded by platelets and neutrophils that are the bases for microthrombi formation." (PMID 36835934, 2023).
Sepsis (continued). "The confirmation of low levels of ADAMTS-13 in neonates with sepsis in further studies could be of great importance, since ADAMTS-13 substitution has been proposed as an adjuvant tool, currently under investigation, in sepsis treatment." (PMID 37886991, 2023). "Additionally, the synthetic ability of the liver is suppressed during sepsis, while various proteases, such as thrombin, plasmin and granulocyte elastase, have been shown to degrade ADAMTS-13." (PMID 37886991, 2023). "The pathogenesis of TTP has been well studied and includes inherited TTP, driven by a gene mutation causing a deficiency in ADAMTS13 production and acquired TTP, which involves an autoantibody, and a decrease in ADAMTS13‐AL, which occurs in sepsis, liver disease, pancreatitis, and cardiac disease." (PMID 36467834, 2022). "Hemostatic changes in ACLF and sepsis greatly overlap: they are both associated with elevated levels of VWF, D-dimer, factor VIII, thrombin-antithrombin and decreased levels of the VWF-regulating protease ADAMTS13 and coagulation factors." (PMID 35223914, 2022). "Sepsis results in overexpressed vWF from ECs and a decreased availability of ADAMTS13." (PMID 35721048, 2022). "Recent studies have suggested a reciprocal correlation between VWF and ADAMTS13 in sepsis." (PMID 33606732, 2021). "The main reason for ADAMTS13 deficiency is acquired autoantibodies causing TTP but there may be additional causes that lower the ADAMTS13 levels, such as sepsis, cardiac surgery, pancreatitis, and liver disease." (PMID 34055510, 2021). "There are some studies showing a role of VWF and ADAMTS13 in pulmonary diseases, sepsis and cancer." (PMID 34134634, 2021). "Previously, the conceptual difference between TTP and “DIC” was supported by the claim that TTP was due to excess of ULVWF as the result of protease ADAMTS13 deficiency, but “DIC” was due to a hemostatic disease associated with endothelial dysfunction as seen in sepsis." (PMID 33061857, 2020). "In patients with sepsis-induced DIC, low molecular weight forms of ADAMTS13 are detected in plasma, indicating that ADAMTS13 deficiency may be due to the proteolysis of proteases in plasma apart from the impairment of biosynthesis." (PMID 33343584, 2020). "The clinical relevance of ADAMTS-13 during sepsis is still unclear." (PMID 31434239, 2019). "Moreover, in a mouse model of sepsis, VWF secretion was a major determinant of ADAMTS-13 decrease and played an important role in sepsis-induced mortality." (PMID 28775254, 2017). "In the normal state, circulating proteases, notably ADAMTS13, degrade vWF into smaller multimers thereby reducing the thrombogenic propensity of vWF; however, in sepsis this homeostatic function may go awry." (PMID 24408224, 2014). "Many studies have evaluated the role of ADAMTS-13 in severe sepsis." (PMID 23537039, 2013). "Analysis of ADAMTS-13 in sepsis would offer help in evaluating the status of the patient." (PMID 23537039, 2013). "It shows that low ADAMTS-13 does not have a sole diagnostic value for TTP only but is also low in other disease states like sepsis." (PMID 23537039, 2013). "Decreased ADAMTS-13 in sepsis has been suggested to be due to several potential mechanisms." (PMID 23537039, 2013). "In contrast, no relevant specific autoantibodies to ADAMTS13 were detected, making unlikely the involvement of an autoimmune process in sepsis-associated ADAMTS13 functional deficiency." (PMID 24238574, 2013). "Sepsis is also associated with low ADAMTS13 activity, although not as low as in TTP (≥10%)." (PMID 39857914, 2025). "As in TTP, children with sepsis associated with low platelets and low ADAMTS13 without overt evidence of DIC or TTP may respond to TPE." (PMID 39857914, 2025). "In this study, we assessed VWF and ADAMTS13 parameters, cVWF levels, and markers of fibrinolytic activity in patients with acute and chronic liver disease across varying disease severities, as well as in patients with sepsis without underlying liver disease." (PMID 41035784, 2025).
Sepsis (continued). "Our study indicates that the vWF/ADAMTS13 ratio may have potential as a surrogate marker of sepsis." (PMID 39200994, 2024). "Furthermore, sepsis patients with such low levels have an ~10% higher risk of death compared with patients who present with no/mild reductions in ADAMTS13 activity levels." (PMID 39274365, 2024). "The massive production of UL–VWF during sepsis may also lead to consumption of ADAMTS-13." (PMID 37886991, 2023). "The mechanism of ADAMTS13 dysregulation in sepsis is unknown, however it has been suggested to be a consequence of reduced synthesis, degradation by thrombin, consumption by massive amounts VWF, or impaired proteolytic activity in the presence of inflammatory mediators." (PMID 33606732, 2021). "Thus, ASM is involved in the dysregulation of ceramide metabolism in endothelial cells leading to macrodomain formation, cytotoxicity, and downregulation of ADAMTS13 expression, which is held to function as an adverse effect to endothelial dysfunction and microthrombus formation in sepsis." (PMID 33553211, 2020). "However, markedly decreased ADAMTS13 levels have been reported in severe sepsis patients without TTP, suggesting that platelet activation due to decreased ADAMTS13 might be observed in DIC patients with severe sepsis." (PMID 30008620, 2018). "Moreover, VWF and ADAMTS13 have been recently proposed as prognostic biomarkers in cardiovascular, metabolic, and inflammatory diseases, such as diabetes, stroke, myocardial infarction, and sepsis." (PMID 28634421, 2017). "In addition, it has been reported that sepsis-associated DIC may reduce ADAMTS13 levels due to consumption resulting from high levels of von Willebrand factor multimers released by perturbed endothelium, whereas in this case ADAMTS13 levels were normal." (PMID 39062862, 2024). "Prior studies have described a role for ADAMTS13, a protein responsible for the cleavage of VWF multimers, in sepsis." (PMID 37159776, 2023). "ADAMTS-13 levels in sepsis have been measured at around 20–43% of normal levels and an imbalance in the VWF/ADAMTS-13 system is observed under inflammatory conditions." (PMID 37886991, 2023). "In sepsis, elevated VWF antigen and activity can be accompanied by reductions in the ADAMTS13 metalloproteinase responsible for cleaving ultra-large VWF multimers into smaller VWF forms." (PMID 33058027, 2021). "Longitudinal changes in the activity and antigen levels of ADAMTS13 and VWF throughout the course of sepsis still remain poorly characterized." (PMID 33606732, 2021). "Lower levels of ADAMTS-13 were seen in patients with SBI and with sepsis, in patients admitted to the ICU, and in patients that needed mechanical ventilator support." (PMID 31434239, 2019). "In this view, it is interesting to observe how in clinical studies on patients with SIRS and sepsis, VWF and ADAMTS13 have shown to be a prognostic biomarker identifying patients with worse outcome and a higher risk of death." (PMID 28634421, 2017). "Reduced level of ADAMTS13, as we showed in this study, has been reported in DIC due to severe sepsis." (PMID 28296884, 2017). "The lack of correlation between the plasma vWF or vWF/ADAMTS13 ratio and IntelliSep results suggests that these two markers probably measure different pathways of activation for sepsis (endothelial activation vs. neutrophil/monocyte activation)." (PMID 39200994, 2024). "At day 1, the vWF/ADAMTS13 ratio was significantly elevated in both patients with and without sepsis in the ICU relative to the healthy controls." (PMID 39200994, 2024). "As microangiopathic changes are not uncommon in patients with sepsis, it is unsurprising to find several studies confirming the finding of low ADAMTS13 levels." (PMID 39274365, 2024). "Moreover, low ADAMTS13 activity observed in TTP needs to be differentiated from aggressive cancer, sepsis, pregnancy, and liver disease." (PMID 39125707, 2024).
Sepsis (continued). "The persistent abnormalities in ADAMTS13 and VWF in sepsis patients discharged from the ICU may contribute to a sustained prothrombotic state." (PMID 33606732, 2021). "Their findings suggested that the ADAMTS-13 levels, as well as the vWF/ADAMTS-13 ratio, combined with the clinical SIRS criteria could provide a valuable tool for sepsis mortality prediction." (PMID 31434239, 2019). "Our study sample showed a significantly lower level of ADAMTS-13 in patients with sepsis versus patients with SBI without sepsis." (PMID 31434239, 2019). "Other authors have measured ADAMTS-13 activity in pediatric patients with sepsis and non-sepsis-induced organ failure, and its activity was significantly lower in sepsis-induced-organ failure." (PMID 31434239, 2019). "Other studies as well have confirmed that ADAMTS-13 activity level can be low in sepsis; however, they state that ADAMTS-13 activity is not an independent predictor of the severity of sepsis (if based on SOFA score) or mortality." (PMID 31434239, 2019). "However, our patients with sepsis, ICU admission, and the need for mechanical ventilatory support had significantly lower levels of ADAMTS-13." (PMID 31434239, 2019). "As sepsis is the inflammatory reaction to infection, we aimed to investigate the levels of ADAMTS-13 in children with serious bacterial infection, to detect the possible use of ADAMTS-13 as a prognostic marker for disease severity in children with SBI." (PMID 31434239, 2019). "In contrast, others have demonstrated that VWF parameters are reciprocally correlated with ADAMTS-13 activity in severe sepsis and septic shock without prognostic value regarding the outcome." (PMID 28775254, 2017). "The ADAMTS13 pattern also differed in infective (sepsis) or noninfective SIRS: septic patients have lower levels of ADAMTS13 than patients with noninfectious SIRS." (PMID 28634421, 2017). "Three studies showed that ADAMTS13 is significantly lower in sepsis than other critically ill nonseptic patients." (PMID 22248019, 2012). "In addition, compared to healthy controls, ADAMTS13 activity was significantly reduced in patients with (47 ± 20%, p < 0.0001) and without (75 ± 23%) (p < 0.01) sepsis compared with that in healthy controls." (PMID 39200994, 2024). "Further clinical studies are needed to clarify if restoration of normal activity levels of ADAMTS13 (i.e., with plasma or recombinant ADAMTS13 infusions) may neutralize VWF-system prevalence and prevent microvascular occlusion and organ failure in patients with SIRS and sepsis." (PMID 28634421, 2017). "As elevated levels of vWF are observed in several inflammatory disease states including sepsis, it is believed that normal or mildly reduced levels of ADAMTS-13 activity may not be sufficient enough to control vWF multimer size." (PMID 23537039, 2013). "Low ADAMTS13 activity is a clinically relevant finding as the magnitude of the decrease in ADAMTS13 is strongly correlated with adverse outcomes in sepsis; approximately a third of patients with sepsis have ADAMTS13 activity levels that are less than 50% of normal." (PMID 39274365, 2024). "Later clinical studies, also in adults and focusing on sepsis without DIC or isolated DIC not specifically related to sepsis, reported decreased ADAMTS13 activity." (PMID 24238574, 2013). "Patients with sepsis, DIC, liver disorders, plasmodium falciparum infection, transplantation, immunosuppression with cyclosporin, and sickle cell disease have been found to have ULVWF multimers with or without significantly decreased levels of ADAMTS13." (PMID 40362344, 2025). "There have been almost no studies of ADAMTS-13 levels in children with SBI, with or without sepsis." (PMID 31434239, 2019).